HMMR (hyaluronan mediated motility receptor)
Diseases named in the same sentence as HMMR in open-access papers (continued):
Sharing a sentence is not in itself a finding about the gene and the disease.
glioblastoma (12 papers, 2014 to 2025). The most malignant astrocytic tumor (WHO grade IV). "HMMR participates in the maintenance of cancer cell stemness and supports the self-renewal and tumorigenic potential of glioblastoma stem cells." (PMID 39086352, 2024). "HMMR maintains the stemness and tumorigenicity of stem-like cells, which is essential for promoting tumorigenesis and angiogenesis in glioblastoma." (PMID 29152086, 2017). "Moreover, PTUPB dramatically suppresses expression of hyaluronan mediated motility receptor (HMMR) in the glioblastoma cell lines and xenograft mouse model, suggesting that the HMMR is the other potential target." (PMID 29152086, 2017). "Moreover, we showed that PTUPB may exert anti-glioblastoma effects by suppressing expression of hyaluronan mediated motility receptor (HMMR) and by targeting epidermal growth factor receptor (EGFR) signaling pathway." (PMID 29152086, 2017). "For example, studies have shown that HMMR was elevated in glioblastoma and that a high expression of HMMR could boost the self-renewal of GBM stem cells (GSCs)." (PMID 35311097, 2022). "Silencing HMMR was also reported to attenuating ERK expression and phosphorylation, acting as an oncogene to maintaining the stemness and tumorigenicity of glioblastoma cell." (PMID 36002694, 2022). "Then, we found that in both glioblastoma cells and xenografts PTUPB suppresses expression of HMMR, a multifunctional oncogenic protein which is highly expressed in malignant tumors." (PMID 29152086, 2017). "In conclusions, we found that the COX-2/sEH dual inhibitor PTUPB suppresses human glioblastoma growth in vitro and in vivo, and dramatically inhibits EGFR signaling pathway and expression of HMMR and stemness markers and regulators." (PMID 29152086, 2017). "Our findings indicated that PTUPB may target the HMMR/SOX2/ZEB1 signaling axis, inhibiting glioblastoma growth." (PMID 29152086, 2017).
acute myeloid leukemia (11 papers, 2012 to 2025). Acute myeloid leukemia (AML) is a group of neoplasms arising from precursor cells committed to the myeloid cell-line differentiation. "HMMR is also an aberrantly expressed gene associated with the cell cycle in proliferating cells of patients with acute myeloid leukemia in vitro." (PMID 34692489, 2021).
ovarian carcinoma (10 papers, 2014 to 2024). A malignant neoplasm originating from the surface ovarian epithelium. "Upregulation of VCAN in CAFs enhanced ovarian cancer cell motility and invasion potential by activating the NF-κB signaling pathway and upregulated expression of CD44, MMP9 and the hyaluronan mediated motility receptor." (PMID 36203562, 2022). "These CAF-related molecules further confer the aggressiveness of ovarian cancer cells through the activation of NF-κB signaling pathway and the up-regulation of CD44, MMP9 and hyaluronan-mediated motility receptor (HMMR)." (PMID 31888563, 2019). "Furthermore, increased expression activity of the hyaluronan-mediated motility receptor (HMMR) gene was reported to augment poor prognosis, aggressive phenotype, and disease progression in ovarian cancer." (PMID 36500178, 2022). "Elevated hyaluronan-mediated motility receptor (RHAMM) has been reported to contribute to disease progression, aggressive phenotype and poor prognosis in multiple cancer types, however, RHAMM’s role in ovarian cancer (OC) has not been elucidated." (PMID 28954627, 2017).
colon carcinoma (9 papers, 2017 to 2025). "Among the 14 model genes, the expression levels of FZD3, CDC25C, CDCA2, NEBL, and HMMR were positively correlated with better prognosis of colon cancer." (PMID 41425852, 2025).
hepatocellular carcinoma (8 papers, 2019 to 2024). A malignant tumor that arises from hepatocytes. "The HMMR, which was as the downstream gene upregulated by testis-specific protein Y-encoded demonstrated that it could be involved in the initiation and development of hepatocellular carcinoma via the activation of HA-HMMR signaling cascade." (PMID 34187556, 2021). "Moreover, another recent report presented evidence that C/EBPα promotes NASH and hepatocellular carcinoma via activation of hyaluronan mediated motility receptor (HMMR) by binding to its promoter." (PMID 37967813, 2024). "Our results had shown that the expression of HMMR was higher in hepatocellular carcinoma tissues than normal liver tissues on mRNA levels and protein levels, and high expression of HMMR in liver hepatocellular carcinoma patients was an adverse prognostic factor." (PMID 34187556, 2021).
fibrosarcoma (7 papers, 2012 to 2025). A malignant mesenchymal fibroblastic neoplasm affecting the soft tissue and bone. "Phosphorylated Smad3 interacts with the YAP/TEAD1-4 complex, increasing the expression of hyaluronic acid-mediated motility receptors (HMMR/RHAMM), which facilitates the progression and metastasis of sarcoma and fibrosarcoma." (PMID 40673277, 2025).
non-small cell lung carcinoma (7 papers, 2016 to 2025). A group of at least three distinct histological types of lung cancer, including non-small cell squamous cell carcinoma, adenocarcinoma, and large cell carcinoma.
breast tumors (4 papers, 2011 to 2023). "Following these suggestions, the expression of HMMR and AURKA or TUBG1 in sporadic breast tumors was found to potentially interact, influencing patients’ survival." (PMID 25830658, 2015).
stomach cancer (4 papers, 2012 to 2025). "Elevated HMMR expression has also been reported to be correlated with poor prognosis in patients with tumors of the stomach, hepatocarcinoma, and B-cell chronic lymphocytic leukemia in adults, among others." (PMID 39859458, 2025). "Based on emerging molecular and functional links of FAM83D to mitosis, we hypothesized that FAM83D promotes gastric tumor growth and progression by stimulating cell cycle progression through binding with HMMR, TPX2, and AUKRA." (PMID 29088801, 2017).
head and neck squamous cell carcinoma (3 papers, 2021 to 2023). A squamous cell carcinoma that arises from any of the following anatomic sites: lip and oral cavity, nasal cavity, paranasal sinuses, pharynx, larynx, and salivary glands. "One study suggested that HMMR may participate in tumor immune response while promoting the progression of head and neck squamous cell carcinoma." (PMID 36750807, 2023).
oral cancer (3 papers, 2020 to 2025). "Hub genes VRK1, NUP37, HMMR, SPC25, and RUVBL1 were identified to be related to oral cancer at both molecular level and clinical levels." (PMID 36052378, 2022).
pancreatic ductal adenocarcinoma (3 papers, 2021 to 2023). An infiltrating adenocarcinoma that arises from the epithelial cells of the pancreas. "Moreover, the expression of HMMR is associated with the progression of cancer, such as RHAMM, and has been suggested as a prognostic factor and a potential therapeutic target for pancreatic ductal adenocarcinoma (PDAC) and pancreatic neuroendocrine (PNET)." (PMID 34745136, 2021).
prostate neoplasm (3 papers, 2019 to 2025). A neoplasm (disease) that involves the prostate gland. "The study aims to investigate 2 gene variants, HMMR-rs299295 and STAB2-rs2271637, with the risk of prostate neoplasms based on a case-control and in silico study in the Mazandaran province (Iran) population." (PMID 40567905, 2025). "The study aims to investigate the relationship between the HMMR-rs299295 (C>T/ A485V) and STAB2-rs2271637 (C>G/ L2401V) gene variants and the risk of prostate neoplasms in the Mazandaran population, North of Iran." (PMID 40567905, 2025). "Our results demonstrate in multiple models of PCa, including cell line and xenograft models of CRPC, and in clinically derived prostate tumours, that targeting HMMR enhances the anti-proliferative efficacy of enzalutamide." (PMID 37673961, 2023). "The mutant alleles of T in HMMR-rs299295 and the G in STAB2-rs2271637 may disrupt protein structures and probably contribute to prostate neoplasm progression." (PMID 40567905, 2025). "Although the provided references do not directly address the association of prostate neoplasm with the ABCC5, HYAL2, and SLC9A1 proteins, it appears that the HMMR-rs299295 and STAB2-rs2271637 variants may play a role in the growth, proliferation, and metastasis of prostate neoplasm." (PMID 40567905, 2025). "According to the findings of this study and the effect of SNPs HMMR-rs299295 and STAB2-rs2271637 in the incidence and progression of prostate neoplasm, studies in a larger sample size and across more ethnicities are suggested to introduce these polymorphisms as a molecular marker." (PMID 40567905, 2025).
sarcoma (3 papers, 2021 to 2025). A usually aggressive malignant neoplasm of the soft tissue or bone. "For example, a zebrafish xenograft assay verified that highly expressed HMMR, under the control of both TGFβ signaling and Hippo pathway, contributed to sarcoma genesis and metastasis." (PMID 35036134, 2021).
COVID-19 (2 papers, 2021 to 2025). A disease caused by infection with severe acute respiratory syndrome coronavirus 2. "Among the ten candidate hub genes, we found that 8 hub genes were differentially upregulated in HBV and COVID-19, so we further narrowed the scope of the study to 8 hub genes, including CDK1, E2F7, E2F8, TYMS, KIF20A, CENPE, TPX2, HMMR." (PMID 40408617, 2025).
myocardial infarction (2 papers, 2021 to 2024). Gross necrosis of the myocardium, as a result of interruption of the blood supply to the area, as in coronary thrombosis. "In a rat model of myocardial infarction, upregulation of HA and HMMR suggests that the HA pathway may play a key role in cardiac regenerative repair." (PMID 39056737, 2024).
neuroblastoma (2 papers, 2017 to 2025). Neuroblastoma (NB) is the most common solid, extracranial childhood tumor. "High HMMR expression correlates strongly with poor prognosis and could be an independent risk factor for neuroblastoma patients." (PMID 41253884, 2025). "A new role for HMMR in DDR within neuroblastoma cells is therefore proposed, requiring further investigation." (PMID 41253884, 2025). "In cultured KELLY neuroblastoma cells, removal of the HMMR protein suppresses proliferation, motility and clonogenic capacity, while xenografts of HMMR-deficient cells imparted longer animal survival compared to wild type cells." (PMID 41253884, 2025). "Lastly, we used phosphoproteomics to begin to explore the potential biochemical roles of HMMR in neuroblastoma cells, confirming that it modulates ERK signaling and potentially also MTOR and DNA damage response (DDR) pathways." (PMID 41253884, 2025). "This supports a possible role of the HMMR gene in the establishment or progression of neuroblastoma." (PMID 41253884, 2025). "HMMR expression was elevated in neuroblastomas compared to normal tissues, benign ganglioblastomas and neural crest-derived tumour pheochromocytoma." (PMID 41253884, 2025). "To investigate the HMMR-Ran pathway in neural cells and tissues, we first utilized the neuroblastoma cell line, SHSY5Y, which is known to polarize NuMA during cell division." (PMID 28994651, 2017). "This raises the hypothesis that HMMR is a direct or indirect modulator of DDR in neuroblastoma cells, a potentially new role for this protein." (PMID 41253884, 2025). "We aimed to define whether HMMR, an oncogene-like protein in several cancers, harbors similar potential in neuroblastoma cells." (PMID 41253884, 2025). "Our studies using cultured primary fibroblasts, directed differentiation of embryonic stem cells, and immortalized cancer cell lines, including neuroblastoma-like cells, uncovered a role for HMMR in the PLK1-dependent positioning pathway at mitotic spindle poles." (PMID 28994651, 2017). "In our search for potentially new drivers with oncoprotein-like behaviour, we have examined the roles of HMMR, also known as RHAMM and CD1684, in neuroblastoma cells." (PMID 41253884, 2025).
psoriasis (2 papers, 2022 to 2023). An autoimmune condition characterized by red, well-delineated plaques with silvery scales that are usually on the extensor surfaces and scalp. "In our study, PTG1, HMMR, PBK, FEN1, DEPDC1 may be some psoriasis-related genes in IL-17A treating of psoriasis." (PMID 37029373, 2023).
acute lymphoblastic leukemia (1 paper, 2025). Leukemia with an acute onset, characterized by the presence of lymphoblasts in the bone marrow and the peripheral blood. "Since B-ALL represents 85% of acute lymphoblastic leukemia cases, determining the levels of HMMR mRNA and protein expression in bone marrow and peripheral blood samples from children with B-ALL is important." (PMID 39859458, 2025).
Cirrhosis (1 paper, 2022). A chronic disorder of the liver in which liver tissue becomes scarred and is partially replaced by regenerative nodules and fibrotic tissue resulting in loss of liver function. "It is concluded that BUB1B, NUSAP1, TTK, HMMR, CCNA2, and KIF2C can be considered as potential novel molecular indicators for the onset and development of HCC, since they are linked to the transition from cirrhosis to HCC." (PMID 36199789, 2022).
colon adenocarcinoma (1 paper, 2021). "In addition, we explored the relationship between HMMR expression and the prognosis of multiple tumors, and found that a high HMMR expression was a protective factor in thymic carcinoma and colon adenocarcinoma, with a higher expression indicating a better prognosis." (PMID 34692489, 2021).
hearing loss (1 paper, 2023). "We also identify four additional novel candidate genes (COL5A1, HMMR, RAPGEF3, and NNT) in which rare variant burden may be associated with hearing loss." (PMID 36656851, 2023).
Lissencephaly (1 paper, 2024). A spectrum of malformations of cortical development caused by insufficient neuronal migration that subsumes the terms agyria, pachygyria and subcortical band heterotopia. "Because HMMR plays such a critical role in mitosis of neural progenitor cells, any loss-of-function Hmmr mutation in humans will likely result in embryonic lethality and prevent the observation of non-mitotic, microtubule-based phenotypes such as corpus callosum malformation or lissencephaly." (PMID 38904660, 2024).
metastatic prostate carcinoma (1 paper, 2019). A carcinoma that arises from the prostate gland and has spread to other anatomic sites. "Previously reported overexpression of HMMR is associated with the development of metastatic prostate cancer (PCa) and castration-resistant PCa." (PMID 31681575, 2019).
neurofibroma (1 paper, 2013). An intraneural or extraneural neoplasm arising from nerve tissues and neural sheaths. "In approximately half of the high-grade tumours and not in low-grade MPNSTs or neurofibromas, hemizygous deletion of the hyaluronan mediated motility receptor (HMMR) gene was reported." (PMID 23328114, 2013).
neutropenia (1 paper, 2018). A decrease in the number of neutrophils found in the blood. "We identified three SNPs in the hyaluronan mediated motility receptor (HMMR) gene that were significantly associated with neutropenia (p < 1.0E-04)." (PMID 29593529, 2018). "HMMR has not been shown to be involved in the mechanism of treatment related neutropenia and the mechanism for how it might be associated with TNFSF13B expression is unclear and should be further explored." (PMID 29593529, 2018). "Interestingly, three SNPs, rs299293, rs299313, and rs299314, which were located in the hyaluronan mediated motility receptor (HMMR) gene, were trans-eQTLs for TNFSF13B, one of the “top” hits identified in the original GWAS for neutropenia." (PMID 29593529, 2018).
nonalcoholic steatohepatitis (1 paper, 2024). "HMMR is involved in cellular adipogenesis, HCC, and nonalcoholic steatohepatitis." (PMID 38694506, 2024).
Sepsis (1 paper, 2025). Sepsis is defined as life-threatening organ dysfunction caused by a dysregulated host response to infection. "The results showed that, compared with the healthy control group, the expression of EXT1, HIF1A and HMMR was upregulated in sepsis, whereas the expression of CD44, EXT2 and SELL was downregulated in sepsis group." (PMID 40672940, 2025).
viral infection (1 paper, 2021). "Several differentially expressed genes between the two trajectories (CTSG, PRC1, DEFA4, KIF15, TCEAL9, HMMR, CEP55, and AZU1) were overexpressed in patients with severe viral infection, but not in those with non-severe viral infection compared to HCs." (PMID 33765435, 2021).